MIR148B (microRNA 148b)
Synonyms: hsa-mir-148b; MIRN148B; mir-148b
Gene: MicroRNA gene on chromosome 12 (54,337,216 to 54,337,314, forward strand). Ensembl gene ENSG00000199122.
Gene Ontology:
Biological process: miRNA-mediated post-transcriptional gene silencing
Cellular component: RISC complex
Homologues: Orthologues: chimpanzee ptr-mir-148b (100% identical), guinea pig MIR148B (95% identical), mouse Mir148b (92% identical), rat Mir148b (92% identical), pig MIR148B (89% identical), rabbit MIR148B (89% identical), macaque mml-mir-148b (83% identical), tropical clawed frog xtr-mir-148b (75% identical), zebrafish dre-mir-148 (59% identical), zebrafish dre-mir-152 (56% identical). Paralogues in human: MIR152 (55% identical), MIR148A (54% identical).